NLRP3 (NLR family pyrin domain containing 3)
Diseases named in the same sentence as NLRP3 in open-access papers (continued):
Sharing a sentence is not in itself a finding about the gene and the disease.
metabolic syndrome (103 papers, 2012 to 2026). A cluster of metabolic risk factors for CARDIOVASCULAR DISEASES and TYPE 2 DIABETES MELLITUS. "In turn, high-fat diets and associated dyslipidemia chronically activate the NLRP3 inflammasome, which plays a role in inducing macrophage activity and release of proinflammatory cytokines like interleukin-1 (IL-1)." (PMID 36615885, 2023). "This study aimed to explore the mechanism of TGQZD on improvement of inflammatory damage and dyslipidemia caused by NAFLD through the CGI-58/ROS/NLRP3 inflammasome pathway." (PMID 35586044, 2022). "Since both NASH and NLRP3 have been linked to metabolic syndrome we have chosen murine models for which we have previously demonstrated that it is suitable for investigation of liver of metabolic syndrome." (PMID 34513923, 2021). "Research efforts have focused on understanding the pathogenic roles of the NLRP3 inflammasome in metabolic syndromes, cardiovascular diseases and neurologic disorders." (PMID 33424855, 2020). "Consistent with previous studies, cells overexpressing XIAP had a reduction in NLRP3 signaling activation, and inflammation-associated dyslipidemia induced by PA treatment was eliminated in these cells." (PMID 31841118, 2019). "Here, we aim to investigate in depth the potential causal link between dyslipidemia and impaired renal tubular function and to uncover the gap relating NLRP3 inflammasome activation and lipotoxicity in renal tubular cells." (PMID 28588189, 2017). "The activation of NLRP3 inflammasomes has been implicated in various pathological conditions, ranging from metabolic syndrome and kidney diseases." (PMID 27867451, 2016). "Indeed, a link between metabolic syndrome, ED, and NLRP3 inflammasome activation as major risk factors for IRI, increasing cardiovascular vulnerability to ischemic events, is established." (PMID 40227195, 2025). "In addition, NLRP3 deficiency alleviated kidney injury through the attenuation of inflammation in the experimental metabolic syndrome." (PMID 37627536, 2023). "Furthermore, the activation of the NLRP3 inflammasome has been implicated in various pathological conditions, ranging from metabolic syndrome to kidney diseases." (PMID 35719709, 2022). "As there is an association between the metabolic syndrome and severity of COVID-19, this might suggest that a heightened activity of NLRP3 caused by a pre-existing condition might further worsen platelet function when infected by the virus." (PMID 36551869, 2022). "Indeed, over-activation of this multi-complex protein has been related to sterile chronic inflammation associated with aging and metabolic syndromes while Nlrp3 gene deficiency promotes healthspan in aging mice." (PMID 35111374, 2022). "NLRP3-deficient mice had altered interactions between the intestinal microbiome and the host, which may influence the progression of symptoms associated with metabolic syndromes." (PMID 31835423, 2019). "Niacin, a vitamin used in the treatment of dyslipidemia, attenuates experimental nonalcoholic steatohepatitis by inhibiting the NLRP3 inflammasome/focal death pathway." (PMID 40433411, 2025). "There is increasing evidence that the NLRP3 inflammasome plays an important role in both inflammation and fibrosis in metabolic syndrome." (PMID 39594557, 2024). "Recent evidence shows mechanistic roles of new biomarkers including a multiprotein complex called nucleotide-binding domain and leucine-rich repeat protein 3 (NLRP3) inflammasome in the pathogenesis of metabolic syndrome." (PMID 38846018, 2024). "Taken together, these findings show how chronic high-fat diets can contribute to metabolic endotoxemia and dyslipidemia through upregulation of key pro-inflammatory factors including NLRP3." (PMID 36615885, 2023). "For instance, IL-18, the designated marker of NLRP3 inflammasome activation status was decreased by 43% in men and women with metabolic syndrome in response to a 12-week aerobic interval training program (three times a week)." (PMID 35273516, 2022).
metabolic syndrome (continued). "Isoliquiritigenin alleviates the metabolic syndrome induced by high-fat diets in mice by inhibiting NLRP3 inflammasome signaling and the symptom induced by intracerebral hemorrhage." (PMID 36577816, 2022). "The results revealed that the top keywords ranked by the strength of citationbursts were “NLRP3 inflammasome” (23.83), “metabolic syndrome” (17.27),“autophagy” (15.24), and “unstable angina” (15.09), etc." (PMID 39077721, 2022). "The NLRP3 inflammasome is a multiprotein complex that is involved in the initiation and development of many diseases, such as metabolic syndrome (MetS) and type 2 diabetes." (PMID 36362220, 2022). "The regulation of NLRP3 inflammasome is important to prevent the detrimental effects of the uncontrolled activation, as in inflammatory diseases like metabolic syndrome." (PMID 33435142, 2021). "In another study, the fructose was used to induce hyperuricemia and dyslipidemia in rats, which activated NLRP3 inflammasome in kidney cells." (PMID 33509217, 2021). "An association between dyslipidemia, LDL oxidation, CD36 expression, ROS generation, thioredoxin-interacting protein (TXNIP) upregulation, and NLRP3 inflammasome activation was demonstrated by DSS exposure in HFD-fed rats." (PMID 33917884, 2021). "Subsequently, the fructose-induced hyperuricemia and dyslipidemia were treated by allopurinol, quercetin and NLRP3 inflammasome inhibitors to improve signaling disturbances and reduce lipid accumulation." (PMID 33509217, 2021). "The activation of the NLRP3 inflammasome is a synchronized interaction between hepatocytes and Kupffer cells that results in dyslipidemia and lipid accumulation in hepatocytes." (PMID 34203484, 2021). "An association between dyslipidemia, the oxidation of LDL, CD36, ROS generation, TXNIP upregulation, NLRP3 inflammasome activation, and dysbiosis has been demonstrated in the present study through the action of DSS in HFD-fed rats." (PMID 33917884, 2021). "The objective, thus, was to investigative circulating NLRP3 levels in Saudi patients with a low-grade inflammatory disorder called metabolic syndrome (MetS)." (PMID 34362072, 2021). "Taken together, these results suggest that MA improved diet-induced lipid abnormality and metabolic syndrome partly through activation of NLRP3 inflammasome in mother rats and offspring." (PMID 34104129, 2019). "Patients with metabolic syndrome have elevated circulating levels of IL-18, a product of NLRP3 inflammasome activation." (PMID 30717382, 2019). "The current study indicated that fat-rich diet-induced NAFLD exhibited lower XIAP and Nrf2 activity levels, then mediated an increase in NLRP3 inflammasomes, resulting in hepatic inflammation and dyslipidemia." (PMID 31841118, 2019). "In a study, using streptozotocin- (STZ-) induced diabetic nephropathy rat model leading to hyperuricemia and dyslipidemia, quercetin was found to block NLRP3 inflammasome activation." (PMID 27672241, 2016). "Therefore, the attenuation of oxidative stress and ROS to suppress CD36-mediated TLR4/6-IRAK4/1 signaling and NLRP3 inflammasome activation by cinnamaldehyde and allopurinol may be a promising therapeutic strategy for the treatment of metabolic syndrome-associated heart disease." (PMID 27270216, 2016). "Dysregulated NLRP3 inflammasome activity contributes to the pathogenesis of diverse inflammatory conditions, including autoimmune disorders, cancer, respiratory diseases, cardiovascular dysfunction, neurodegeneration, and metabolic syndromes." (PMID 41531891, 2026). "This study investigates whether inclisiran can mitigate the cardiotoxic effects of anthracyclines and trastuzumab through reduction of NLRP3 activation and MyD88 signaling, independently of its effects on dyslipidemia." (PMID 40724868, 2025). "Moreover, the role of recent biomarkers including NLRP3 inflammasome and its downstream cytokines including IL-1β in the pathogenesis of metabolic syndrome as well as its comorbid diseases are warranted." (PMID 38846018, 2024).
metabolic syndrome (continued). "In this study, the authors demonstrated for the first time that empaglifozin treatment was able to improve glycemic levels and pathophysiological changes in metabolic syndrome, in addition to reducing NLRP3 complex activation, with IL-1β inhibition in a dose-dependent manner." (PMID 39412512, 2024). "Moreover, the activation of purinergic 2X7 receptors (P2X7R) in conjunction with the NLRP3 inflammasome has been identified as a significant contributor to renal inflammation and injury within the context of metabolic syndrome-related renal ailments." (PMID 39619610, 2024). "For that reason, this study was conducted in ApoE-/- mice, which have a genetic predisposition to develop chronic inflammation, including metabolic syndrome as a useful tool to explore the therapeutic effects of a novel selective NLRP3 antagonist in lean NAFLD." (PMID 34513923, 2021). "The role of NLRP3 inflammasome in metabolic syndrome and T2DM can be split into two subcategories." (PMID 33546399, 2021). "In conclusion, this study suggests a sexual disparity in the circulating levels of NLRP3, with a trend of increasing circulating NLRP3 levels with increasing MetS components observed only in females, influenced mostly by adiposity and dyslipidemia components of MetS." (PMID 34362072, 2021). "Inflammasome activation by fructose could also be the result of increased Glut5 activity, which induces TXNIP to form the activated complex of ASC with NLRP3, consequently inducing dyslipidemia, hepatic inflammation, and lipid accumulation." (PMID 34203484, 2021). "However, a consensus on precisely how the inflammasome sensor proteins implicated in the metabolic syndrome and diabetic conditions, NLRP1 and NLRP3, come to be activated in these states, has yet to be reached." (PMID 29515457, 2018). "Therefore, targeted interventions aimed at modulating NLRP3 inflammasome and oxidative stress may offer promising strategies to mitigate ischemic damage in patients with metabolic syndrome." (PMID 40227195, 2025). "Also, in humans, elevated circulating levels of IL-18, a product of the activation of the nucleotide binding and oligomerization domain-like receptor family pyrin domain-containing 3 (NLRP3) inflammasome, have been identified in patients with metabolic syndrome." (PMID 36816031, 2023). "Of relevance in relation to a poor lifestyle possibly leading to worse acute disease and long COVID, is that sterile activation of NLRP3 may occur in the metabolic syndrome, leading to generalised inflammation (“metainflammation”), which is also associated with mitochondrial dysfunction." (PMID 36551869, 2022). "Targeting NLRP3 inflammasome to reduce steatosis, sterile liver inflammation, and consequent fibrosis may be an underlying mechanism for the therapeutic action of FTZ on NASH and possibly on other end-organ damage induced by metabolic syndrome." (PMID 30140364, 2018). "In both obese murine models and human liver tissues, enhanced expression of NLRP3 inflammasome components, increased CASPASE‐1 activity, and elevated levels of IL‐1β have been observed, correlating directly with the severity of metabolic syndrome phenotypes." (PMID 41169786, 2025). "Among the mediators of this inflammatory cascade, the NLRP3 inflammasome has emerged as a key integrator of mitochondrial stress, redox imbalance, immune signaling, and metaflammation in IRI and metabolic syndrome." (PMID 40722993, 2025). "Animal experiments demonstrate that secondary bile acids inhibit the NLRP3-mediated inflammatory vesicle in macrophages through the activation of TGR5 receptors and thereby ameliorate metabolic syndrome." (PMID 40831637, 2025). "This furthers NLRP3 inflammasome activation, ATMφ SASP, dyslipidemia, NASH, atherosclerosis, and metabolic syndrome." (PMID 39063184, 2024).
metabolic syndrome (continued). "In this study, we not only found that APN improved dyslipidemia, but also showed that APN alleviated inflammation and lipid accumulation by inhibiting the NLRP3/ NF-κB signaling pathway." (PMID 37198205, 2023). "Therefore, the activated NLRP3 inflammasome might be involved in metabolic syndrome." (PMID 30717382, 2019). "This study highlighted the critical role of the gut microbiota in the pathogenesis of systemic autoinflammation and metabolic diseases by showing how the NLRP6 and NLRP3 inflammasomes negatively control the development of MASH and metabolic syndrome by altering them." (PMID 39070791, 2024). "Given our long-lasting interest in FTZ, a widely used herbal remedy for metabolic syndrome and hyperlipidemia and related complications in China, we tested whether FTZ exerts its action through inhibition of NLRP3 inflammasome formation and activation." (PMID 30140364, 2018). "New anti-inflammatory compounds, such as NLR family pyrin domain containing 3 (NLRP3) inflammasome inhibitors–1,3,4-oxadiazol-2-one derivative 5 (INF200), have shown notable improvements in glucose tolerance and systemic inflammation in preclinical models of diet-induced metabolic syndrome." (PMID 40943638, 2025). "The activation of NLRP3 inflammasome leads to cell pyroptosis and inflammatory cytokines secretion and gets involved in the development of many diseases, such as neuroinflammation and metabolic syndrome, but the drugs targeting NLRP3 are not clinically available for now." (PMID 35252186, 2022).
peritonitis (103 papers, 2009 to 2026). Inflammation of the peritoneum (tissue that lines the abdominal wall and covers most of the organs in the abdomen). "To further study the protective effect of Vitenegu acid in NLRP3 associated diseases, we next determined if Vitenegu acid can effectively inhibit NLRP3 inflammasome activation in a mouse peritonitis model." (PMID 37153555, 2023). "We have identified the β-blocker carvedilol as a novel autophagy inducer that inhibits the NLRP3 inflammasome in macrophages and ameliorates NLRP3-associated peritonitis in mice." (PMID 35669789, 2022). "The production of IL-1β in peritonitis and septic shock induced by i.p. injection of LPS is associated with NLRP3 inflammasome activation." (PMID 33414479, 2021). "We further demonstrated that F240B exerts in vivo anti-inflammatory activity in a mouse model of uric acid crystal-induced peritonitis, which is an NLRP3 inflammasome-associated disorder." (PMID 33424855, 2020). "We investigated the in vivo anti-inflammatory activity of F240B using an NLRP3 inflammasome-associated MSU crystal-induced mouse peritonitis model." (PMID 33424855, 2020). "As CVL inhibited the NLRP3 inflammasome in macrophages, we further investigated the in vivo effect of CVL using a mouse model of MSU-mediated peritonitis, which is associated with the NLRP3 inflammasome." (PMID 30186288, 2018). "Oral administration of CVL also attenuated inflammatory responses in a mouse model of NLRP3-associated peritonitis." (PMID 30186288, 2018). "Consistent with that, TRIM31 deficiency facilitated NLRP3 inflammasome activation, enhanced IL-1β secretion and thus aggravated alum-induced peritonitis in vivo." (PMID 27929086, 2016). "In vivo, SENP6 deficiency exacerbates NLRP3 activation and lung inflammation in lipopolysaccharide-induced endotoxic shock-associated lung injury, and enhances inflammatory responses in alum-induced peritonitis." (PMID 41531891, 2026). "HSP70 deficiency leads to the worsening of NLRP3-dependent peritonitis in mice." (PMID 30874540, 2019). "Additionally, we assessed the in vivo effects of CVL in a mouse model of NLRP3-associated peritonitis by analysing the peritoneal recruitment of neutrophils and the levels of cytokine in the lavage fluids." (PMID 30186288, 2018). "We first show that ITO-NP–caused peritonitis in mice depended on NLRP3 inflammasome." (PMID 27194621, 2016). "Consequently, TRIM31 deficiency enhances NLRP3 inflammasome activation and aggravates alum-induced peritonitis in vivo." (PMID 27929086, 2016). "In the human NLRP3 129S6 mice in a peritonitis model, we show that BAL-0598 dose dependently blocks IL-1β release but not IL-6." (PMID 40892070, 2025). "Using humanized NLRP3 mice, we show that a derivative of BAL-0028, BAL-0598, inhibits NLRP3 activation in vivo in a peritonitis model." (PMID 40892070, 2025). "To examine NLRP3 inhibition in vivo, we performed a well-characterized model of peritonitis using i.p. injection of LPS followed by ATP, where IL-1β production in the peritoneal cavity is NLRP3 dependent." (PMID 40892070, 2025). "We also analyzed the role of Ufl1 in NLRP3 inflammasome‐driven peritonitis by i.p. injection of Alum." (PMID 39985286, 2025). "Recent studies on its anti-inflammatory properties have reported its ability to inhibit the activation of the NLRP3 inflammasome and reduce LPS-induced peritonitis in mice." (PMID 40736248, 2025). "As an NLRP3 alkylator, Bot-4-one enhances the ubiquitination of NLRP3 contributing to the suppression of NLRP3 inflammasome in bone marrow derived-macrophage (BMDMs) and monosodium urate-induced peritonitis mouse model." (PMID 38421496, 2024). "Studies have shown that carvedilol has antioxidant effects and can protect against peritonitis by inhibiting NLRP3 inflammasome activation and macrophage pyroptosis." (PMID 39619569, 2024).